AFP (alpha fetoprotein)
Diseases named in the same sentence as AFP in open-access papers (continued):
Sharing a sentence is not in itself a finding about the gene and the disease.
hypospadias (2 papers, 2023 to 2025). Hypospadias is the displacement of the urethral meatus on the ventrum of the penis. "Studies have indicated that the levels of alpha-fetoprotein (AFP) and free beta human chorionic gonadotrophin (free beta-HCG) in the maternal serum during early and middle gestation are associated with the likelihood of fetal hypospadias." (PMID 39980698, 2025).
leukemia (2 papers, 2010 to 2023). A malignant (clonal) hematologic disorder, involving hematopoietic stem cells and characterized by the presence of primitive or atypical myeloid or lymphoid cells in the bone marrow and the blood. "Human mononuclear leukemia cells (THP-1) and monocytes from healthy donors were used to analyze the effect of AFP on the macrophages’ phenotype and phagocytosis." (PMID 36911723, 2023).
Leydig cell tumor (2 papers, 2024). A sex cord-stromal tumor occurring in the testis and rarely in the ovary. "While cases of ovarian Sertoli–Leydig cell tumors associated with raised levels of alpha-fetoprotein are rare, they are reported to be the most common alpha-fetoprotein-producing ovarian non-germ cell tumor." (PMID 39336518, 2024).
Lymphatic Metastasis (2 papers, 2016 to 2025). Transfer of a neoplasm from its primary site to lymph nodes or to distant parts of the body by way of the lymphatic system. "Univariate analysis revealed that lymphatic metastasis, PT, MVI, HBV, GAR, ALB, AST, Child-Pugh grade, neutrophils, CEA, AFP, and CA19-9 were significant risk factors." (PMID 41210683, 2025). "These variables were then included in the multivariate analysis, which demonstrated that lymphatic metastasis, MVI, GAR, PT, AFP, CEA, and HBV were independent prognostic risk factors for patients with cHCC-CCA (P-value < 0.05)." (PMID 41210683, 2025).
mucinous tumor (2 papers, 2020 to 2024). "Although the ultrasound images were similar to those of ovarian serous or mucinous tumors, these tumors were negative for serum AFP." (PMID 38966065, 2024).
myositis (2 papers, 2021 to 2023). "Our study showed serum tumor markers (CEA and AFP) and autoimmune markers (ANA) were associated with malignancies in patients with myositis." (PMID 33633147, 2021).
neonatal hemochromatosis (2 papers, 2022 to 2023). Neonatal hemochromatosis is a disease in which too much iron builds up inthe body. "Depending on the primary metabolic derangements observed, patients with DGUOK deficiency have been misclassified as neonatal hemochromatosis (hyperferritinemia and elevated alpha-fetoprotein) and tyrosinemia type 1 among other disorders." (PMID 38027095, 2023).
NUT Carcinoma (2 papers, 2017 to 2025). "We eventually reached the diagnosis of the peculiar entity of NUT midline carcinoma, but the differential diagnosis was quite challenging also because alpha-fetoprotein is not reported as a marker of NUT midline carcinoma." (PMID 28407756, 2017).
PEComas (2 papers, 2025). "Distinguishing AFP-elevated PEComas from HCC presents diagnostic challenges." (PMID 40313453, 2025).
pineal germinoma (2 papers, 2022 to 2023). "Importantly, total regression of the pineal germinoma, accompanied by β-HCG and AFP levels returning to normal range, was observed 4 months after chemotherapy." (PMID 38066820, 2023).
pineal tumor (2 papers, 2021 to 2022). "For 12 patients, preoperative serum and CSF levels of pineal tumor markers (AFP and β-HCG) were collected." (PMID 32504201, 2021).
pineoblastoma (2 papers, 2023 to 2025). Pineoblastoma is a rare, malignant type of supratentorial primitive neuroectodermal tumor (sPNET), found mainly in children (less than 10% of cases are reported in adults), and located in the pineal region of the brain but that can metastasize along the neuroaxis. "Only 2 pineoblastomas showed mild elevation of AFP, which may be related to the fact that AFP itself is less specific and often raised in malignant tumors." (PMID 37706201, 2023).
placental insufficiency (2 papers, 2019 to 2022). Failure of the placenta to deliver an adequate supply of nutrients and oxygen to the fetus. "Recent reports of biomarkers in maternal blood related to early-onset placental insufficiency include pregnancy-associated plasma protein-A (PAPP-A), alpha-fetoprotein (AFP), inhibin A, placental growth factor (PlGF), uric acid, and free beta- or total human chorionic gonadotropin." (PMID 30984110, 2019).
porphyria (2 papers, 2023). Porphyria is a group of diseases in which substances called porphyrins build up, negatively affecting the skin or nervous system. "NTBC reduces the risk of HCC and porphyria attacks and leads to a decrease in AFP levels." (PMID 37686577, 2023). "AFP serves as an early marker of hepatic remodeling, neoplastic transformation, and porphyria seizures in this condition." (PMID 37686577, 2023). "Whether AFP might have prognostic capacities in subgroups of patients with porphyria is unclear." (PMID 36765753, 2023).
primary immunodeficiency (2 papers, 2016 to 2025). "In patients with elevated IgM or AFP levels—or in those whose clinical and laboratory findings do not fit a defined primary immunodeficiency phenotype—whole exome sequencing is essential for timely and accurate identification." (PMID 41044616, 2025).
rectal adenocarcinoma (2 papers, 2016 to 2026). "Laboratory examination (e.g., AFP, CEA, CA125, CA199, TDIL, and DBIL) showed no abnormalities except in 1 patient (case 4), who had concurrent gastric stromal tumor and rectal adenocarcinoma and presented with an elevated CEA level of 231 ng/mL (normal: 0–5 ng/mL)." (PMID 27610132, 2016).
rhabdomyosarcoma (2 papers, 2013 to 2024). A rare aggressive malignant mesenchymal neoplasm arising from skeletal muscle. "In rhabdomyosarcoma, tumoral markers including alpha-fetoprotein, beta-human chorionic gonadotropin and carcinoembryonic antigen are usually normal." (PMID 23561643, 2013).
serous adenocarcinoma (2 papers, 2018 to 2021). An adenocarcinoma that is characterized by the presence of papillary patterns and cellular budding. "In both cases, the epithelial component was most consistent with serous carcinoma, at least in part, but some areas were difficult to classify and might represent a transition between AFP+ and Müllerian components." (PMID 34977100, 2021). "We hypothesized that AFP+ EC might also be associated with HER2 overexpression, but the frequency of HER2 positivity by immunohistochemistry was not significantly different from that reported for serous carcinoma." (PMID 34977100, 2021).
Sertoli-Leydig cell tumor (2 papers, 2020 to 2022). A sex cord-gonadal stromal tumor consists of leydig cells; sertoli cells; and fibroblasts in varying proportions and degree of differentiation. "Final histopathological diagnosis was a moderately differentiated Sertoli-Leydig cell tumor of the ovary with alpha-fetoprotein-producing cells without hepatocytic or intestinal epithelium differentiation." (PMID 35450124, 2022).
signet ring cell carcinoma (2 papers, 2021 to 2025). A usually aggressive, poorly differentiated invasive adenocarcinoma characterized by the presence of malignant glandular cells in which the nucleus is pressed to one side by the presence of intracytoplasmic mucus. "There were 18 baseline parameters used for propensity score matching, including sex, age, BMI, hemoglobin, platelet, leukocyte, pre-albumin, total protein, albumin, CA125, CA199, CA724, CEA, AFP, tumor differentiation, signet ring cell carcinoma component, Borrmann type and clinical N stage." (PMID 34497768, 2021).
spina bifida aperta (2 papers, 2014 to 2015). "The study described 11 alpha-1 fetoprotein (AFP) fragments that were downregulated and 35 AFP fragments that were upregulated in AFSs from embryos with spina bifida aperta." (PMID 25789708, 2015). "Specifically, they found 11 alpha-1 fetoprotein (AFP) fragments that were downregulated and 35 AFP fragments that were upregulated in AFSs from embryos with spina bifida aperta." (PMID 25054433, 2014).
Stroke (2 papers, 2025 to 2026). Sudden impairment of blood flow to a part of the brain due to occlusion or rupture of an artery to the brain. "Notably, serum alpha‐fetoprotein (AFP) was not measured during the initial stroke workup." (PMID 41487984, 2026).
Superior Vena Cava Syndrome (2 papers, 2017 to 2023). A condition that occurs when the obstruction of the thin-walled SUPERIOR VENA CAVA interrupts blood flow from the head, upper extremities, and thorax to the RIGHT ATRIUM. "He had life-threatening superior vena cava syndrome, and his serum AFP level was 765 ng/mL." (PMID 37781207, 2023).
testicular germ cell tumours (2 papers, 2019 to 2023). "Traditional serum tumour markers alpha‐fetoprotein (AFP), beta‐human chorionic gonadotropin (β‐hCG) and lactate dehydrogenase (LDH) play an integral role in the diagnosis and management of testicular germ cell tumours (TGCTs)." (PMID 36569509, 2023). "Serum tumour markers alpha fetoprotein (AFP), beta human chorionic gonadotropin (bHCG), and lactate dehydrogenase (LDH) represent valuable tools for the clinical management of testicular germ cell tumours (GCTs)." (PMID 31275973, 2019).
thrombophilia (2 papers, 2008 to 2023). A condition characterized by an abnormally high level of thrombi. "High AFP levels have also been associated with thrombophilia." (PMID 36846633, 2023).
thyroid disorders (2 papers, 2017 to 2025). "Sertoli–Leydig cell tumors in humans may be associated with thyroid disorders and DICER1 gene mutations and show positive results for blood inhibin and alpha-fetoprotein (AFP)." (PMID 41451336, 2025).
thyroid neoplasms (2 papers, 2024 to 2025). "In contrast, secondary thyroid neoplasms typically do not display these markers; but instead, express unique indicators tied to their tissue of origin, such as alpha-fetoprotein (AFP) and hepatocytes." (PMID 39050581, 2024). "Histologically, the left thyroid lobe biopsy of our patient presents negative markers for primary thyroid neoplasms (TTF-1 and TG) and positive markers for hepatitis-associated disease (AFP and GPC3), confirming the presence of poorly differentiated metastatic HCC." (PMID 40575170, 2025).
Tyrosinemia type 1 (2 papers, 2022 to 2023). "Nevertheless, increased AFP levels are well documented in several metabolic conditions, most notably tyrosinemia type-1." (PMID 35455589, 2022).
ureteric obstruction (2 papers, 2018 to 2025). "A rise in serum alpha-fetoprotein, refractory to second-line chemotherapy, was accompanied by subsequent development of ureteric obstruction, ascites, and radiological evidence of peritoneal metastases." (PMID 29992073, 2018).
vascular cancer (2 papers, 2022). A malignant neoplasm arising from the blood vessels. "If AFP is not decreased significantly and does not become negative after a period, and the change in AFP-L3 is not obvious, the operation may be incomplete; there may be residual tumor at the excision edge, vascular cancer plug, satellite nodules, or extrahepatic metastasis." (PMID 35307694, 2022).
abortion (1 paper, 2015). the ending of pregnancy by removing a fetus or embryo before it can survive outside the uterus. "In this study, we examined the serum levels of inhibitory cytokines in normal pregnancy and recurrent spontaneous abortion, and analyzed the correlation of IL-35 with estrogen and alpha-fetoprotein (AFP) levels." (PMID 26042836, 2015). "The levels of IL-35, IL-10, TGF-β, estradiol (E2), unconjugated estriol (uE3) and AFP were analyzed in 120 normal pregnancies, 40 women suffering recurrent spontaneous abortion, 40 postpartum healthy women and 40 non-pregnant women by enzyme-linked immunosorbent assay (ELISA)." (PMID 26042836, 2015).
Acrokeratosis paraneoplastica (1 paper, 2007). "Production of Granulocyte-Colony Stimulating Factor, alpha-fetoprotein, paraneoplastic pemphigus and leucocytosis, Acrokeratosis paraneoplastica (Bazex's syndrome) are reported." (PMID 17620118, 2007).
acute cholecystitis (1 paper, 2025). "Acute cholecystitis showed a strong association with elevated levels of leukocytes, alkaline phosphatase, CA 19-9, CEA, AFP, and CA-125." (PMID 40332145, 2025).
adenocarcinoma of the renal (1 paper, 2014). "Elevated serum levels of AFP, CEA and CA19-9 have been reported in several studies of adenocarcinoma of the renal pelvis and were considered to be effective prognostic biomarkers." (PMID 25364445, 2014).
adenosquamous carcinoma (1 paper, 2022). A carcinoma composed of malignant glandular cells and malignant squamous cells. "Furthermore, p‐hTERT expression was associated with immature and aggressive features, such as adenosquamous carcinoma (lung and pancreas), invasive type of cancer (lung), high serum alpha‐fetoprotein level (liver), and triple‐negative status (breast)." (PMID 35094384, 2022).
adrenal carcinoma (1 paper, 2019). A carcinoma involving a adrenal gland. "In HE staining, the morphology of two tumors were slightly different; therefore, we evaluated two HCC markers (GPC3 and AFP) and two adrenal carcinoma markers (vimentin and Melan-A) via IHC staining." (PMID 31696344, 2019).
amenorrhea (1 paper, 2018). The absence of menses in a woman who has achieved reproductive age. "A total of 51.4% of live births in Optum used the date of an alpha fetoprotein test or nuchal ultrasound to estimate start date; 17.9% used an amenorrhea or urine pregnancy test record; 28.1% used the average gestational age estimate." (PMID 29389968, 2018).
amyloidosis (1 paper, 2025). A disorder characterized by the localized or diffuse accumulation of amyloid protein in various anatomic sites. "In the SMC-calc vs. SMC comparison based on limma, clusters related to high-density lipoprotein (HDL) assembly (PF4V1, APOA1, LPXN, AFP, A2M, and MMP1) and amyloidosis (CX3CL1, APOE, PLIN3, TGFBI, and CH25H) were identified." (PMID 41301179, 2025).
Arrhythmia (1 paper, 2016). Any cardiac rhythm other than the normal sinus rhythm. "Median time to first arrhythmia was 74 h (IQR 26–149 h) for NSVT, 22 h (IQR 5–73 h) for sustained VT, 22 h (IQR 7–64 h) for SP, 31 h (IQR 11–82 h) for AFP, and 40 h (SD 10–118 h) for HGHB." (PMID 26883019, 2016).
Atrophy (1 paper, 2016). Any weakening or degeneration, especially through lack of use. "Moreover, elevated serum AFP and apparent cerebellar atrophy were observed in these two cases." (PMID 27644330, 2016).
autoimmune encephalitis (1 paper, 2025). Inflammation of the brain secondary to an immune response triggered by the body itself. "Markers of autoimmune encephalitis, including CA19-9, carcinoembryonic antigen (CEA), alpha-fetoprotein (AFP), and CA125, were within normal limits." (PMID 40843296, 2025).
bile duct carcinoma (1 paper, 2012). "Patients: HCC vs. (chronic HCV infection, bile duct carcinoma and healthy)Test: sera GOLPH2 detection using ELISA, AFP not tested.Outcomes: no usable data." (PMID 22244200, 2012). "Patients: HCC vs. (HCV, bile duct carcinoma and healthy)Tests: sera GOLPH2 levels by ELISA, unclear whether AFP tested or not.Abstract; no clear data reported." (PMID 22244200, 2012).
bladder adenocarcinoma (1 paper, 2022). "There are also documented cases of bladder adenocarcinomas that have shown both immunoreactivity for AFP and elevated serum AFP levels." (PMID 35027045, 2022).
bladder urothelial carcinoma (1 paper, 2025). "Here, we report a case of bladder urothelial carcinoma with significantly elevated AFP levels and review the literature to discuss the diagnosis, treatment, and prognosis." (PMID 40406259, 2025). "The serum AFP levels fell rapidly after the operation, indicating an AFP-producing urothelial carcinoma of the urinary bladder." (PMID 40406259, 2025). "It is also reported that an AFP-producing bladder transitional cell carcinoma (TCC) with lung and bone metastases behaved aggressively and had a poor prognosis." (PMID 40406259, 2025). "Whether an AFP elevation affects the response and prognosis of bladder urothelial carcinoma is still unclear and requires further investigation." (PMID 40406259, 2025). "This is the fourth case of urothelial carcinoma of the bladder with AFP elevation." (PMID 40406259, 2025). "AFP-producing urothelial carcinoma of the bladder is very rare." (PMID 40406259, 2025). "In conclusion, AFP-producing bladder urothelial carcinoma is rare, and the mechanism and pathophysiology remain unclear and require further investigation." (PMID 40406259, 2025). "AFP-producing urothelial carcinoma of the bladder is an extremely rare entity." (PMID 40406259, 2025). "Bladder urothelial carcinoma with AFP elevation is rare and has rarely been reported." (PMID 40406259, 2025). "We report a case of bladder urothelial carcinoma with significantly elevated AFP levels." (PMID 40406259, 2025).
bone tumor (1 paper, 2010). "Even with large tumor burden before both bone tumor excisions, the highest recorded serum AFP level was 15.39 ng/mL." (PMID 20500842, 2010).
breast tumor (1 paper, 2024). "Alpha-fetoprotein and cancer antigen 125 (CA125) are the standardized breast tumor markers." (PMID 38794187, 2024).
cardiomyopathy (1 paper, 2025). A disease of the heart muscle or myocardium proper. "The other four variables selected through ML approach (i.e., DDD of TKI on index date ≥ 1, concomitant use medications associated with hyperkalemia, AFP ≥ 9 ng/ml, cardiomyopathy) in the training dataset were relatively less important and also not listed as the statistical associated factors." (PMID 40817221, 2025). "In particular, the other 10 factors also contributed more than 0.14 chance in the statistical best model but not for those least important factors in the ML best model (AFP ≥ 9 ng/mL, DDD of TKI on index date ≥ 1, Cardiomyopathy were all < 0.1)." (PMID 40817221, 2025).
cervical tumors (1 paper, 2025). "Clinically, women with cervical tumors and elevated AFP need to consider the possibility of cervical HAC." (PMID 40740864, 2025).
choledocholithiasis (1 paper, 2023). Presence or formation of gallstones in the common bile duct. "The levels of AFP, Ferritin, and HBeAg were notably increased, while the levels of Albumin and CHE were significantly decreased in HCC patients compared to choledocholithiasis patients." (PMID 38188679, 2023). "The levels of ALT, AST, AFP, T-bil, Ferritin, and HBeAg were significantly elevated, while the levels of Albumin and CHE were markedly reduced in HCC patients compared to choledocholithiasis patients." (PMID 38188679, 2023).
chronic cholangitis (1 paper, 2024). Cholangitis that is persistent and long-standing. "Most patients were asymptomatic, while a few have showed right upper abdominal pain or symptoms like chronic cholangitis; alpha-fetoprotein may be elevated." (PMID 37864655, 2024).
CNS germinomas (1 paper, 2014). "In addition, up to 85–90% of patients with CNS germinomas test negative for serologic hCG and AFP." (PMID 25045548, 2014).
colonic adenocarcinoma (1 paper, 2026). "CAED is a rare subtype of colonic adenocarcinoma characterized by increased AFP production and expression of at least one enteroblastic marker, including AFP, glypican 3, or SALL4." (PMID 41589237, 2026).
congenital hemangioma (1 paper, 2020). A hemangioma present and fully formed at birth. "The congenital hemangioma size may decrease and serum AFP level often falls rapidly after birth, while CHB dose not." (PMID 32756095, 2020). "In our study, several patients were misdiagnosed as congenital hemangioma at admission, which might result from our lacking recognition of CT characteristics of CHB and neglecting the importance of serial measurements of AFP in the neonatal period." (PMID 32756095, 2020).
congenital nephrosis (1 paper, 2025). "Since the 1970s, AFP measurement has been used for the prenatal diagnosis of congenital nephrosis." (PMID 40669863, 2025).